CDC42 (cell division cycle 42)
Diseases named in the same sentence as CDC42 in open-access papers (continued):
Sharing a sentence is not in itself a finding about the gene and the disease.
esophageal cancer (5 papers, 2016 to 2021). A primary or metastatic malignant neoplasm involving the esophagus. "Several genes/pathways have been implicated to esophageal cancer migration, such as Cdc42, HGF/SF, Androgen receptor, RhoA, Rac-1, and Cdc42, VEGF, HER2, PLCE1, ABCG2/V-ATPase, MMS19." (PMID 28147311, 2017). "In this study, we have demonstrated for the first time the essential requirement for the small GTPases Ras, Rho and cdc42 in leptin-induced Akt activation in oesophageal cancer cells." (PMID 33582946, 2021). "Another recent study unraveled the tumor-suppressor role of miR-107 in esophageal cancer by targeting CDC42." (PMID 32577165, 2020). "Results indicated that the expression of four target genes (CCND1, CASP3, EGFR, and CDC42) was markedly upregulated in esophageal carcinoma." (PMID 32412911, 2020). "Expression analysis of miR-196a-5p and miR-1-3p targets in TCGA using the UALCAN tool showed that CCND1, CASP3, EGFR, and CDC42 were overexpressed in esophageal carcinoma, compared to normal esophagus samples." (PMID 32412911, 2020).
glomerulosclerosis (5 papers, 2016 to 2022). A hardening of the kidney glomerulus caused by scarring of the blood vessels. "The imbalance in activation of the small GTP-binding proteins Rac1 and Cdc42 (Cdc42 regulates the podocyte actin cytoskeleton), validates the link between podocyte injury and proteinuria as well as glomerulosclerosis at another level." (PMID 36091814, 2022). "Recent studies have indicated that in vivo podocyte-specific deletion of Cdc42 leads to congenital nephrotic syndrome and glomerulosclerosis." (PMID 30621321, 2019). "Mechanistic studies revealed that miRNA-25 exerted its protective role in DKD mainly through targeting inhibition of cell division cycle 42 (CDC42) expression, a downstream effector of Ras that can lead to congenital nephrotic syndrome and glomerulosclerosis." (PMID 35845986, 2022). "Furthermore, Cdc42 might take part in the glomerulosclerosis tubular interstitial fibrosis." (PMID 30621321, 2019). "Recent studies have indicated that podocyte-specific deletion of Cdc42 in vivo, but not of RhoA or Rac1, leads to congenital nephrotic syndrome and glomerulosclerosis." (PMID 26986510, 2016).
hemophagocytic lymphohistiocytosis (5 papers, 2020 to 2025). "Previously, four variants in the RHO GTPase CDC42 were discovered in patients affected by syndromes generally characterized by neonatal-onset of cytopenia and auto-inflammation, including hemophagocytic lymphohistiocytosis and rash in the most severe form (NOCARH syndrome)." (PMID 39550374, 2024). "A disease characterized by neonatal-onset cytopenia, autoinflammation, rash, and episodes of hemophagocytic lymphohistiocytosis (NOCARH) has been recently described in 4 unrelated patients carrying the same de novo heterozygous missense mutation in Cell division cycle 42 (CDC42) at p.Arg186Cys." (PMID 33717395, 2021).
Hydrocephalus (5 papers, 2016 to 2023). Hydrocephalus is an active distension of the ventricular system of the brain resulting from inadequate passage of CSF from its point of production within the cerebral ventricles to its point of absorption into the systemic circulation. "Inactivation of Cdc42 leads to hydrocephalus, causes death during the postnatal stage and disrupts ependymal cell differentiation, resulting in aqueductal stenosis." (PMID 37008045, 2023). "The brain-specific KO of CDC42 eventually causes hydrocephaly or holoprosencephaly, demonstrating the importance of CDC42 in establishing and maintaining intricate tissue structures during CNS development." (PMID 36206843, 2022). "A previous research has shown ciliary mutant phenotypes, including hydrocephalus and pericardial edema in the zebrafish with Cdc42 knockdown." (PMID 36056002, 2022).
immune deficiency (5 papers, 2018 to 2025). "A variable degree of immunodeficiency has been primarily linked to the variants affecting the switch II domain in the CDC42 gene." (PMID 37347054, 2023). "Herein, we report an another patient presenting with distinctive symptoms of TKS (OMIM #616737) due to the heterozygousp.Tyr64Cys variant in CDC42 and the clinical phenotype with congenital malformations, immunodeficiency, and gastrointestinal disorders." (PMID 37347054, 2023). "Recent reports have shown that Cdc42 to be essential for the activation and function of mature B cells in a mouse model of primary immune deficiency." (PMID 29713426, 2018). "Primary clinical diagnosis was mainly combined immunodeficiencies (48.3%) and the majority of cases were molecularly assigned to the CDC42 pathway (64.8%)." (PMID 40860338, 2025).
ischemic stroke (5 papers, 2011 to 2023). A stroke disorder caused by obstruction of blood flow to the brain, due to thrombotic (local blood clot formation) or embolic (due to a blood clot or other material traveling from another site) event. "Downregulation of CDC42 attenuates neuronal apoptosis in ischemic stroke." (PMID 36831829, 2023). "Additionally, an in vitro study reported that the activation of CDC42 promoted the migration of endogenous neural stem/progenitors cells after ischemic stroke, which facilitates the recovery of injured brain tissue." (PMID 35547377, 2022). "Endoplasmic reticulum protein-29 and CdC-42 were expressed only in endothelial progenitor cells of healthy subjects, and elongation factor-2 was identified only in endothelial progenitor cells from patients with ischemic stroke." (PMID 34948066, 2021). "However, no investigation has shown an association between CDC42 and DWI-FLAIR mismatch in ischemic stroke." (PMID 36831829, 2023). "Moreover, CDC42 and RHOA serve as key modulators in the cascade of ischemic stroke involving apoptosis, excitotoxicity, platelet function, neuroinflammation, and blood–brain barrier (BBB) balance, emphasizing CDC42 and RHOA as key endogenous mediators in the penumbra." (PMID 36831829, 2023).
Macrothrombocytopenia (5 papers, 2013 to 2023). "MK-specific Rac and Cdc42-double knockout mice exhibit macrothrombocytopenia due to impaired microtubule formation." (PMID 34504210, 2021). "Megakaryocyte- and platelet-specific deletion of the Cdc42 gene in mice results in mild macrothrombocytopenia and shortened platelet lifespan, but Cdc42−/− platelets form filopodia with normal morphology on fibrinogen coated surfaces." (PMID 23359340, 2013).
myocardial infarction (5 papers, 2021 to 2024). Gross necrosis of the myocardium, as a result of interruption of the blood supply to the area, as in coronary thrombosis. "For instance, in the context of myocardial infarction (MI), a study revealed that M1-BMMs-EVs played a role in inhibiting angiogenesis and MI post-MI by modulating the MALAT1/miR-25-3p/CDC42 direction." (PMID 39323624, 2024).
osteoporosis (5 papers, 2009 to 2025). A condition of reduced bone mass, with decreased cortical thickness and a decrease in the number and size of the trabeculae of cancellous bone (but normal chemical composition), resulting in increased fracture incidence. "Patients with CDC42 mutations presented with leukopenia, osteoporosis, hypotonia, and developmental delay." (PMID 40488176, 2025). "CDC42 is essential for the correct dynamics of actin rings in osteoclasts and for bone resorption in vitro and in vivo in the mouse; conversely, excessive activity of CDC42 causes osteoclast hyperactivity and osteoporosis." (PMID 34869381, 2021). "Although currently, there are reports about the natural product, which could play a therapeutic role in bone loss diseases (osteoporosis and osteolysis) through the regulation of Rac1/2 and Cdc42 during osteoclasts cytoskeletal structuring." (PMID 32578854, 2020). "Although currently, there have been no reports on the natural product, which could play a therapeutic role in bone loss diseases (osteoporosis and osteolysis) through the regulation of Rac1/2 and Cdc42 during osteoclasts cytoskeletal structuring." (PMID 32578854, 2020). "Based on our findings, we propose that targeting Sirt5 to block Cdc42 activity may be an option for the treatment of osteoporosis." (PMID 38274381, 2024). "Recently, Wang and colleagues reported that mice deficient in a negative regulator of Cdc42 (Cdc42GAP) exhibited constitutively elevated Cdc42 expression and phenotypes consistent with premature aging, including: osteoporosis, muscle atrophy, and impaired wound-healing." (PMID 19245677, 2009).
psoriasis (5 papers, 2018 to 2025). An autoimmune condition characterized by red, well-delineated plaques with silvery scales that are usually on the extensor surfaces and scalp. "Evans syndrome and psoriasis were among the most common autoimmune clinical presentations in the RAC2 GTPase group compared to the CDC42 GTPase group." (PMID 40860338, 2025). "A possible mechanism for this is that PGGT1B-deficient macrophages migrate to the epidermis more easily during psoriasis, which leads to the activation of Cdc42, NF-κB signaling, and NLRP3 inflammatory corpuscles." (PMID 40430037, 2025). "Previous studies have found that increased serum Cdc42 levels in psoriasis patients reflect disease severity." (PMID 40430037, 2025). "Reduced PGGT1B levels can increase the expression of CDC42, which further activates NLRP3 inflammation in macrophages through NF-κB signaling, further aggravating the inflammatory state of psoriasis." (PMID 40430037, 2025).
renal failure (5 papers, 2016 to 2026). "Cdc42 deletion results in massive neonatal proteinuria, kidney failure, and associated death within 2 weeks of birth, podocyte-specific RhoA and Rac1 deletion mutants are conspicuously healthy." (PMID 26986510, 2016). "The kidney-specific Cdc42 knockout mice exhibited early postnatal death due to renal failure." (PMID 29124443, 2018). "The up-regulated CDC42 inhibited cell apoptosis and promoted proliferation of porcine and chicken GCs, whereas mice lacking CDC42 in podocytes developed congenital nephropathy and died from renal failure within 2 weeks after birth." (PMID 36362009, 2022).
retinal degeneration (5 papers, 2011 to 2024). Degeneration of the retina. "Particularly, loss of Cdc42 in the developing mouse retina at E10.5 resulted in severely disrupted lamination after E14.5, retinal degeneration and affected visual function postnatally." (PMID 39650797, 2024). "Together, these results show that the peripheral retina of Cdc42-KD mice exhibited progressive retinal degeneration that was also reflected by a significant loss of function." (PMID 23372671, 2013). "However, neuronal knockdown of Cdc42 during development caused loss of the outer limiting membrane in the peripheral retina and progressive retinal degeneration." (PMID 28671996, 2017). "The perinuclear localization of CDC42 in TUNEL-negative photoreceptor cells during retinal degeneration seems to be a general reaction of the retina to degeneration." (PMID 22128240, 2011). "In summary, we showed that CDC42 accumulates in the perinuclear region of photoreceptors during retinal degeneration." (PMID 22128240, 2011). "This suggests that the activation of Rac1 and Cdc42 pathways precedes retinal degeneration." (PMID 27775019, 2016). "We show that absence of CDC42 during development caused improper retinal lamination, and resulted in progressive retinal degeneration, loss of function and vascular disorganization." (PMID 23372671, 2013). "This may suggest that survival mechanisms attempted, but were not capable to provide prolonged protection for neuronal cells and to prevent retinal degeneration in Cdc42-KD mice." (PMID 23372671, 2013). "Retinal degeneration induces the accumulation of CDC42 in the perinuclear region of photoreceptors." (PMID 22128240, 2011). "Second, the rod-specific knockdown of CDC42 did not prevent photoreceptor loss in the light-induced or inherited model of retinal degeneration—in contrast to the rod-specific ablation of RAC1, which protected rods after excessive light exposure." (PMID 22128240, 2011). "Furthermore, the persistent gliosis and gliotic scar formation in Cdc42-KD mice may also be detrimental and contribute to retinal degeneration through the secretion of pro-inflammatory cytokines such as TNFα and CCL2." (PMID 23372671, 2013). "A similar CDC42 staining pattern was observed in all tested inherited mouse models (rd1, rd10, and VPP) of retinal degeneration." (PMID 22128240, 2011). "We have shown that CDC42 ablated retinas are not properly laminated, lack obvious adherens junctions between photoreceptors and Müller glia cells, and undergo severe retinal degeneration." (PMID 23372671, 2013). "Lack of CDC42 affected organization of the developing retina as early as E17.5, prevented correct tissue lamination, and resulted in progressive retinal degeneration and severely reduced retinal function of the postnatal retina." (PMID 23372671, 2013). "To be able to directly compare the results obtained for CDC42 to the RAC1 data published recently, we used the same experimental approach as published and analyzed retinal degeneration in mice, specifically in rod photoreceptors, with a conditional Cdc42 knockdown." (PMID 22128240, 2011). "Since it has been shown in other systems that CDC42 can participate in the endothelin and LIF signaling pathways, we tested whether the ablation of CDC42 in rods might affect the molecular response during retinal degeneration." (PMID 22128240, 2011). "Since RAC1 and CDC42 are members of the same family of proteins, and since they can have overlapping functions, we addressed the question of whether CDC42—similar to RAC1—might also influence processes involved in retinal degeneration." (PMID 22128240, 2011). "CDC42 accumulated in the perinuclear region of terminal deoxynucleotidyl transferase dUTP nick end labeling–negative photoreceptors during retinal degeneration induced by excessive light exposure and in the rd1, rd10, and VPP mouse models of retinitis pigmentosa." (PMID 22128240, 2011).
retinal degeneration (continued). "The knockdown of Cdc42 did not affect retinal morphology or function in the adult mice and did not influence photoreceptor apoptosis or molecular signaling during induced and inherited retinal degeneration." (PMID 22128240, 2011). "Here, we show that CDC42, another member of the small GTPase family, does not play a major role in photoreceptor death, even though CDC42 specifically localized to the perinuclear region of some photoreceptor cells during induced and inherited retinal degeneration." (PMID 22128240, 2011).
colorectal adenocarcinoma (4 papers, 2012 to 2025). The most common type of colorectal carcinoma. "Integration with machine learning‐selected hub genes identified ESR2 and CDC42 as promising molecular targets potentially underlying tumor and normal tissues differences in colorectal adenocarcinoma." (PMID 41246859, 2025). "A marked decrease of active Cdc42 and Rac1 correlated with the high invasive potential of the cell lines established from metastatic sites of colorectal adenocarcinoma (LoVo, SKCo1, SW620 and CoLo205)." (PMID 23144867, 2012). "Additionally, CDC42 has been reported to be highly expressed in colorectal adenocarcinoma and downregulate inhibitor of DNA binding 4 (ID4) through an epigenetic mechanism." (PMID 26515597, 2015).
coronary heart disease (4 papers, 2022 to 2024). "For example, one study discloses that CDC42 negatively associates with Th17 cells in patients with coronary heart disease." (PMID 38476381, 2024). "Another study explored the correlation between CDC42 and T helper (Th) 2 cells, Th17 cells, and blood lipids in patients with coronary heart disease." (PMID 35547377, 2022). "Additionally, reduced CDC42 levels were found in coronary heart disease patients compared to controls, indicating inflammation." (PMID 36831829, 2023). "In addition, clinical research suggests that CDC42 is positively correlated with Th2 cells but negatively correlates with Th17 cells in patients with coronary heart disease." (PMID 35547377, 2022).
epilepsy (4 papers, 2016 to 2017). A brain disorder characterized by episodes of abnormally increased neuronal discharge resulting in transient episodes of sensory or motor neurological dysfunction, or psychic dysfunction. "Based on recent publications, various small GTPases have been identified to contribute to the progression of epilepsy, including Cdc42, RAB39B." (PMID 28255556, 2017). "The pathological plasticity of neuronal spines and synapses is important in the pathological process of epilepsy; thus, we studied the activation levels of Rac1 and Cdc42 to explore whether Rac1 and Cdc42 are regulated by the miR-132/p250GAP pathway in our SRED model of cultured hippocampal neurons." (PMID 27579184, 2016).
Huntington disease (4 papers, 2022 to 2023). Huntington disease (HD) is a rare neurodegenerative disorder of the central nervous system characterized by unwanted choreatic movements, behavioral and psychiatric disturbances and dementia. "Cdc42 is a major determinant of spine formation and maintenance, and aberrant Cdc42 signaling in the striatum is implicated in multiple neurological diseases, such as Huntington's disease." (PMID 35415964, 2022). "In adjacent normal tissue, CDC42 and co-expressed genes are linked to KEGG pathways such as 'oxidative phosphorylation', 'non-alcoholic fatty liver disease', 'Huntington's disease', and others." (PMID 37365287, 2023).
leukemia (4 papers, 2019 to 2023). A malignant (clonal) hematologic disorder, involving hematopoietic stem cells and characterized by the presence of primitive or atypical myeloid or lymphoid cells in the bone marrow and the blood. "Increased expression and activity of Cdc42 are associated with the transformation of HSCs/P to AML in leukemia cells." (PMID 34405015, 2021). "Introduction of Cdc42 Activity Specific Inhibitor, CASIN, enhances the eradication of ALL leukemia stem cells by AraC+QC and prolongs the survival of both primary and secondary transplanted recipients without affecting normal long-term human hematopoiesis." (PMID 34836965, 2021). "Recently, CDC42 was unveiled to control AML cell polarity and division asymmetry, and represents a useful target to alter leukemia-initiating cell fate for differentiation therapy." (PMID 31645843, 2019).
liver cancer (4 papers, 2013 to 2025). An epithelial or non-epithelial malignant neoplasm that arises from the liver. "In mouse models, specific knockdown of CDC42 on hepatocytes can cause chronic liver disease, such as hepatomegilia, bile duct tissue damage, and even liver cancer." (PMID 39990675, 2025). "SDF-1α expression in liver cancer can activate small GTPases, including CDC42, through interacting with CXCR470." (PMID 28067275, 2017).